RN7SL825P (RNA, 7SL, cytoplasmic 825, pseudogene)
Gene: Miscellaneous RNA gene on chromosome 10 (31,992,087 to 31,992,381, reverse strand). Ensembl gene ENSG00000239731.
Homologues: Orthologues: chimpanzee Metazoa_SRP (99% identical), macaque Metazoa_SRP (90% identical). Paralogues in human: RN7SL1 (84% identical), RN7SL2 (84% identical), RN7SL3 (84% identical), RN7SL220P (82% identical), RN7SL431P (81% identical), RN7SL7P (81% identical), RN7SL769P (81% identical), RN7SL127P (80% identical), RN7SL408P (80% identical), RN7SL45P (80% identical), RN7SL126P (80% identical), RN7SL230P (80% identical), and 703 more.